RNU6-451P (RNA, U6 small nuclear 451, pseudogene)
Gene: Small nuclear RNA gene on chromosome 2 (230,587,121 to 230,587,227, forward strand). Ensembl gene ENSG00000199791.
Homologues: Orthologues: macaque U6 (88% identical), rat LOC120095351 (80% identical), mouse Gm24086 (66% identical), guinea pig U6 (60% identical). Paralogues in human: RNU6-1209P (85% identical), RNU6-1147P (81% identical), RNU6-115P (81% identical), RNU6-340P (81% identical), RNU6-618P (81% identical), RNU6-797P (81% identical), RNU6-1131P (80% identical), RNU6-1180P (80% identical), RNU6-11P (80% identical), RNU6-28P (80% identical), RNU6-37P (80% identical), RNU6-500P (80% identical), and 1285 more.